CRP (C-reactive protein)
Diseases named in the same sentence as CRP in open-access papers (continued):
Sharing a sentence is not in itself a finding about the gene and the disease.
diabetes (continued). "The univariate analysis identified that age, diabetes mellitus, PD duration, HGB, lymphocyte, ALB, ALT, CRP, D-D, FIB, folate, VitB12 levels, PNI, NLR, PLR, LMR, and SII were significant factors associated with the ADL score." (PMID 34093411, 2021). "To date, several risk factors for stroke in patients with ESRD on dialysis have been reported, and include diabetes mellitus (DM), hypertension, atrial fibrillation (Af), old age, anemia, malnutrition, asymmetric dimethylarginine, and elevated C-reactive protein (CRP)." (PMID 34068165, 2021). "Lower DNA methylation level were associated with higher serum urate levels, as were as higher levels of body mass index (BMI), blood pressure, triglycerides, liver enzymes, C-reactive protein (CRP), and incident diabetes in their respective EWAS." (PMID 34887389, 2021). "Compared with the CAC (<100) group, the CAC (>400) group had higher proportions of older patients, hypertension and diabetes mellitus patients, longer dialysis duration, higher MAP, higher levels of hs-CRP, ALP, and phosphate (P < 0.05)." (PMID 34976409, 2021). "Among new-onset patients with diabetes receiving standard statin therapy, liraglutide together with metformin improved lipid distribution of LDL and C-reactive protein (CRP) in atherosclerosis." (PMID 34131405, 2021). "As compared with patients without PSCI, those with it were older, had a greater prevalence of diabetes mellitus, education years <12, and LA, and had higher baseline NIHSS score, WBC count, uric acid, and Hs-CRP level." (PMID 35185753, 2021). "Age, diabetes mellitus, smoking, body mass index, RDW-CV, CRP, proteinuria, AKI, and usage of ARB/ACEI were also significant factors." (PMID 33782522, 2021). "Higher level of urinary MA, age, CRP, lower level of serum albumin, ABI, eGFR, CLI, diabetes, cerebral infarction, and CHD were related to CVLE, and statin therapy was related to CVLE in Cox univariate analysis (p<0.05)." (PMID 34707745, 2021). "Model 1 + adjustments for CRP, HDL cholesterol, diastolic blood pressure, smoking behavior, diabetes, PTDM, and SQUASH score." (PMID 34091671, 2021). "None of the following parameters differed among the three groups: age, sex, BMI, smoking, drinking, diabetes mellitus, hypertension, hyperlipidemia, Scr, LDL-c, TG, TC, FPG, CRP, ALT, and AST levels." (PMID 34239687, 2021). "Patients with MACCEs showed higher age, TGs/HDL-C ratio, hypersensitive C-reactive protein (hs-CRP), FPG, TGs and creatinine, longer duration of diabetes, and higher prevalence of previous stroke and percutaneous coronary intervention (PCI) history." (PMID 33573649, 2021). "Serum levels of ANGPTL8, resistin, BMI, blood pressure, duration of diabetes, glycosylated hemoglobin (HbA1c), fasting blood glucose (FPG), hypersensitive C-reactive protein (hs-CRP), lipid profile, liver, and kidney function tests were assessed." (PMID 34603198, 2021). "Preoperative routine blood analysis showed an increased level of CRP for PJI patients (92 mg/dl), and 44% of the PJI patients had diabetes mellitus." (PMID 34421900, 2021). "Higher level of urinary MA, age, CRP, lower level of serum albumin, ABI, diabetes, and CHD were related to MACE, and higher urinary MA level, age, lower ABI, cerebral infarction, and CHD were related to CVLE." (PMID 34707745, 2021). "The patients who needed ICU were elderly and had higher frequencies of diabetes, higher basal and peak values of hs-cTnI, LDH, CRP, procalcitonin and D-dimer levels, and also higher ferritin and lower albumin values." (PMID 33501850, 2021). "This indicated that if the patients' IL-37, CRP, NT-pro BNP, hs-cTnI, and diabetes can be well controlled, the prognosis of patients can also be improved." (PMID 34580597, 2021). "We performed a multivariate logistic regression analysis including age, hypertension, diabetes mellitus, dialysis duration, MAP, hs-CRP, ALP, phosphate, sclerostin, and miRNA-29b." (PMID 34976409, 2021).
diabetes (continued). "The FPG, 2hPG, HbA1C, CRP, IL-6, Visfatin, JAZF1, HOMA-IR, EAT thickness, and baPWV of the Complication Group were all higher than those of the Diabetes Group and the Healthy Control Group (P < 0.05, respectively)." (PMID 33722242, 2021). "Higher level of urinary MA, age, CRP, lower level of serum albumin, ABI, diabetes, and CHD were related to MACE, and statin therapy was related to MACE in multivariate analysis (p<0.05)." (PMID 34707745, 2021). "In this study, CCVD was correlated with the higher urinary level of MA, age, CRP, lower level of serum albumin, eGFR, ABI, diabetes, cerebral infarction, and CHD." (PMID 34707745, 2021). "The differences in age, sex, hypertension, diabetes, smoking, drinking, BMI, WBC, TC, LDL-C, HDL-C, and ApoA1 were not statistically significant in the three groups, but the differences in TG and CRP were statistically significant (P < 0.001)." (PMID 34235188, 2021). "As an inflammatory microenvironment, diabetes is characterized by 2-3-fold elevated concentrations of tumor necrosis factor (TNF), IL-6 and C-reactive protein (CRP) in the peripheral blood." (PMID 34975496, 2021). "Traits highlighted due to several of these factors include: C reactive protein (CRP), BMI, diabetes, alanine aminotransferase and reticulocyte blood cell measures." (PMID 34301914, 2021). "Patients in the MACCE group had a higher incidence of diabetes, hypertension, left main and/or three-vessel disease, with higher levels of FBG, HbA1c, hs-CRP and reduced LVEF (all P<0.05)." (PMID 34290672, 2021). "The risk was slightly attenuated but persisted after adjustments for age, sex, education years, diabetes mellitus, baseline NIHSS score, DWI-ASPECTS 0–7, uric acid, and Hs-CRP level (OR, 2.00; 95% CI 1.03–4.20; p = 0.046)." (PMID 35185753, 2021). "Higher level of urinary MA, age, CRP, D-dimer, lower level of serum albumin, BMI, ABI, eGFR, CLI, diabetes, cerebral infarction, and CHD were related to CCVD in Cox univariate analysis (p<0.05)." (PMID 34707745, 2021). "The following anamnestic and hematochemical data were also considered: age, gender, hypertension, diabetes mellitus, smoking habit, therapy, low-density lipoprotein (LDL)-C, kidney failure and hs-CRP." (PMID 34829465, 2021). "Higher level of urinary MA, age, CRP, D-dimer, lower level of serum albumin, BMI, ABI, eGFR, CLI, diabetes, and CHD were related to MACE, and statin therapy was related to MACE significantly in Cox univariate analysis (p<0.05)." (PMID 34707745, 2021). "Clinical data analysis showed that elevated C-reactive protein (CRP), tumor necrosis factor- (TNF-) α, and interleukin- (IL-) 6 were the most common inflammation indicators in diabetes-related angiopathies." (PMID 34938814, 2021). "In the MLR for walking speed, the included variables comprise aerobic physical activity, diabetes, hypothyroidism, protein intake, and serum TSH and CRP." (PMID 32774854, 2020). "Diabetes, impaired fasting glucose, HbA1c, hypertension, male sex, BMI, cTnT, CACS, WBC count, the number of all leukocyte types analyzed, and the levels of CRP, IL‐6, and TNF‐α were reproducibly, positively correlated with the QRS‐T angles." (PMID 32638456, 2020). "CAN was used as the dependent variable, and the duration of diabetes, HbA1c, FBG, TC, TGs, HDL-DL, LDL-C, SUA, Hs-CRP, LH, FSH, TSH, FT3 and FT4 were used as the independent variables for Pearson correlation analysis." (PMID 32968413, 2020). "A recent review of 17 clinical studies by Carver and Jones also confirmed that older age, diabetes, higher serum levels of inflammatory markers (LDH, CRP), and coagulopathy with higher serum D-dimer levels are associated with a higher risk for ARDS." (PMID 33244300, 2020). "Patients in the lowest quartile of mtDNA copy numbers had a 3.43‐fold (95% CI 1.24–9.50, P = 0.018) higher risk for cancer mortality compared with those in quartiles 2–4 (data adjusted for age, smoking status, CRP, prevalent CVD and diabetes)." (PMID 32037598, 2020).
diabetes (continued). "Participants with high AACS were more likely to be older, with higher BMI and a longer PD duration, more prevalent in hypertension, diabetes, and CVD, with lower serum albumin and HDL, but greater hs-CRP and TG." (PMID 32349690, 2020). "We also performed a subgroup analysis in groups divided according to age, gender, the presence of diabetes, CVD and CKD stages, and albumin and CRP levels." (PMID 33173137, 2020). "High-sensitivity C-reactive protein (hs-CRP) levels are lower in HNF1A-MODY and have been tested in some studies to discriminate HNF1A-MODY from other types of diabetes, although more data are needed." (PMID 32528556, 2020). "The CD4+ cell counts in the diabetes group were lower than those in the other two groups, while the levels of LDH and hs-CRP were higher." (PMID 33062712, 2020). "The close pathological and physiological tie between COPD and metabolic diseases is also revealed in the fact that such systemic inflammation markers as CRP, TNF-a and IL-6 would increase in diabetes and play an important role in the development of diseases." (PMID 33108241, 2020). "Seven factors were identified as significant predictors using univariate analysis, including age, onset age of diabetes, SBP, DBP, TC, CRP, and HSP27 (all P < 0.05)." (PMID 32334520, 2020). "The univariate analysis suggested that age, gender, diabetes, hypertension, types of statins, HDL-C (STDEV), CRP (mean), LDL-C (mean), creatinine and uric acid were all risk factors for the mean value of NLR during follow-up." (PMID 32493321, 2020). "Smoking, alcohol consumption, diabetes, high-density lipoprotein (HDL), high-sensitivity C-reactive protein (hs-CRP) and estimated glomerular filtration rate (eGFR) were identified as independent determinants of urinary 2Py/N1-MN in RTR." (PMID 32041099, 2020). "Stepwise multivariable linear regression analyses with backward elimination revealed smoking, alcohol consumption, diabetes, HDL, hs-CRP and eGFR as independent determinants of urinary 2Py/N1-MN in RTR." (PMID 32041099, 2020). "And also, diabetes reversed the positive correlation between ferritin and LDL-C in the lower CRP level (0-3.0 mg/L)." (PMID 32280714, 2020). "Case-control differences were assessed by logistic regression and survival by Cox regression, adjusted for age, gender, smoking, diabetes, ejection fraction, PLP, eGFR and CRP." (PMID 31923223, 2020). "The results remained significant after adjustment for age, current smoking, CRP, prevalent CVD and diabetes (Model 3: HR = 2.62, 95% CI 1.27–5.40, P = 0.008)." (PMID 32037598, 2020). "Covariates selected for model of ICU admission included SBP, blood urea nitrogen, P, ferritin, diabetes, CAD, ALB, CRP." (PMID 30759782, 2019). "Results were essentially the same when models were concurrently adjusted for gender, age, apoB concentration, diabetes, past CVD history, CRP, and eGFR." (PMID 30813431, 2019). "The following variables were significantly associated with the IL‐18 concentration at three out of the four occasions during follow‐up: male sex, obesity, diabetes and biomarkers of renal function (cystatin C), and inflammation (WBC, CRP‐hs, GDF‐15, Il‐10)." (PMID 31596518, 2019). "A number of studies have also linked alterations in certain proteins, such as C-reactive protein (CRP), γ-glutamyl transpeptidase (GGT) or adiponectin, to diabetes." (PMID 31446444, 2019). "Age, smoking, diabetes, SBP, MAP, hs-CRP, LDL-C, uric acid, and WBC were positively correlated with baPWV." (PMID 30992389, 2019). "Covariates after backward selection in model of cardiovascular event included Age, SBP, UA, Hb, diabetes, CAD, CRP." (PMID 30759782, 2019). "All the results were analyzed adjusting for age, gender, BMI, HR, SBP, DBP, family history, smoking status, FPG, TC, TG, HDL, LDL, HCY, hs-CRP, UA, CAD, PAD, diabetes, hypoglycemic drugs, and lipid-lowering drugs." (PMID 31341663, 2019).
diabetes (continued). "A linear regression analysis was calculated to predict HDL-C, LDL-C, and TG levels, based on the following independent variables: Gram stain, CRP, WBC, BMI, diabetes, gender, and statin therapy." (PMID 30982158, 2019). "Our present study indicated that the progression of diabetes mellitus, FPG, HbA1c, and CRP levels differed significantly between the groups with low and high serum 25(OH)D concentration (all P < 0.05), which is consistent with previous findings." (PMID 31871946, 2019). "The combination of MASP, apolipoprotein E (apoE) and adiponectin improved diabetes prediction on top of both reference models, while prediabetes prediction was improved by MASP plus CRP on top of the HbA1c model." (PMID 30599058, 2019). "Covariates of adjusted model of hospitalization included SBP, ALT, UA, K, P, ferritin, diabetes, ALB, CRP." (PMID 30759782, 2019). "The 68 studies that examined diabetes/inflammation measures (HOMA-IR, insulin, glucose, C reactive protein, interleukin-6, alanine transaminase and the 71 studies examining cardiac measures (eg, lipids, cholesterol, blood pressure) will be reported separately." (PMID 31473614, 2019). "In the univariate binary logistic regression analysis, the history of diabetes, FPG, HbA1c, hs-CRP, Crouse score, 5-mC and 5-hmC levels were correlated with coronary atherosclerosis." (PMID 31123222, 2019). "Another study also shows that sitagliptin reduces serum CRP levels via inhibiting the activation of NF-κB in T2DM, partially improving endothelial dysfunction in patients with uncontrolled diabetes and CVD." (PMID 31208420, 2019). "Hazard ratios reveal risk with increasing age, gender (males > females), apoB concentration, diabetes, past history of CVD, CRP concentration, and decreasing eGFR." (PMID 30813431, 2019). "In this group, the adjusted HR for diabetes per SD increase in GDF-15 was 1.21 (95% CI 1.09, 1.35; p < 0.001), and with additional adjustment for CRP this HR was 1.16 (95% CI 1.04, 1.29; p = 0.009)." (PMID 30350239, 2019). "Patients with diabetes were older and more likely to be male, with shorter duration of PD, higher BMI, higher rate of CVD comorbidity, lower HDL cholesterol, and higher CRP levels." (PMID 30850727, 2019). "The incidence of lower extremity artery plaque; degree of arteriostenosis; course of diabetes; and the levels of fasting plasma glucose (FPG), HbA1c, and CRP differed significantly between the low- and high-concentration serum 25(OH)D groups (all P < 0.05)." (PMID 31871946, 2019). "Inflammation contributes to the pathogenesis of diabetes, in which SAA and other inflammatory markers, including CRP, TNF, and MCP-1, increase in parallel with urinary albumin." (PMID 30899260, 2019). "Univariate analysis showed that age, MetS, INS, Lg(hs-CRP), Lg(IL-6), FFAs, Lg(APN), SBP, DBP, body mass index (BMI), smoking, diabetes, family history of hypertension, and dyslipidemia were differed significantly between CVD and non-CVD cases." (PMID 31191115, 2019). "The circulating levels of C-reactive protein (CRP), interleukin-1β (IL-1β) and IL-6 are elevated in type 2 DM even before the onset of diabetes." (PMID 29694426, 2018). "In those patients with diabetes, plasma levels of RBP4 were positively correlated with HbA1c (r = 0.347, P<0.0001), BMI (r = 0.163, P=0.001), Hs-CRP (r = 0.302, P<0.001), and duration of illness (r = 0.179, P<0.001)." (PMID 30135138, 2018). "Inflammatory biomarkers, such as white cell counts (WBC), C-reactive protein (CRP), tumor necrosis factor-α (TNF-α), and interleukin-6 (IL-6), were showed to be correlated with prevalent and incident diabetes." (PMID 29651306, 2018). "The proportion of men, subjects with diabetes and hypertension, as well as age, levels of triglycerides, RDW, hs-CRP, hemoglobin, and BMI were all higher in those with than those without arterial CVD." (PMID 31249941, 2018).
diabetes (continued). "The frequency of males, patients with hypertension and diabetes, smoking, alcohol drinking, family history of cerebrocardiovascular events, and the level of TGs, TC, LDL, hs-CRP, and GLU were higher in stroke groups than in control groups (P < 0.05)." (PMID 29850543, 2018). "Compared with NC, the levels of serum inflammation indexes like CRP, IL6, IL8, TNF-α, and CCL2 were significantly increased (p < 0.05), while IL10 levels were significantly decreased (p < 0.05) in diabetes groups (MC, WP and SCCOPs-treated groups)." (PMID 29316680, 2018). "Exercise induced a decrease in the pro-inflammatory cytokines, such as tumor necrosis factor α (TNF-α) and IL-6, C-reactive protein (CRP), thereby assisting the prevention or mitigation of such chronic-degenerative diseases such as obesity and diabetes." (PMID 30666216, 2018). "Participants with a higher RDW tended to be older and female, and to have a higher BMI and CRP levels, lower ASM and hemoglobin, higher amount of smoking pack-years, less MVPA, and a higher prevalence of hypertension, diabetes, and CVD." (PMID 30065297, 2018). "We have shown the significant correlation between PTX3 and existence of diabetes, HbA1c, UAE, PAC and high-sensitive CRP in total population of this study." (PMID 29715313, 2018). "As supported by a cross-sectional survey on 1914 elder individuals aged 70–79 years without overt diabetes and cardiovascular events, there was a positively graded relationship between number of MetS diagnostic components and increased circulating levels of CRP and IL-6." (PMID 29670915, 2018). "This was also true after the adjustment for age, sex, body mass index (BMI), hypertension, diabetes, smoking, family history of CAD and high sensitivity C-reactive protein (hs-CRP)." (PMID 29892007, 2018). "Similar results were obtained after adjusting for confounding factors such as age, sex, BMI, smoking, drinking, hypertension, diabetes mellitus, heart failure, vascular disease, LAD, AF type, LDL, and CRP." (PMID 29235504, 2017). "When stratifying based on diabetes status, WBC, sodium, creatinine, glucose, and CRP were significantly different between the cellulitis and NF groups, while hemoglobin was not significantly different." (PMID 28611889, 2017). "Interleukin-6 (IL-6), another pro-inflammatory cytokine released by adipocytes, in turn induces a rise in C-reactive protein (CRP) from the liver; elevated levels of these inflammatory markers have been shown to predict the onset of diabetes." (PMID 28817063, 2017). "In clinical practice, increased levels of C-reactive protein (CRP) and IL-6 have been suggested to predict the development of type 2 diabetes mellitus (DM)." (PMID 29147465, 2017). "Inflammatory mediators such as TNF-α, IL-6, and CRP, which are elevated in COPD, are also increased in diabetes." (PMID 27335596, 2016). "Age (<70 vs. ≥70 year), gender, diabetes, hypertension, elevated PLR, CRP level, tumor size, intravesical therapy agents and tumor multiplicity were not significant predictor in the univariate analysis." (PMID 27385379, 2016). "We evaluated the lipid profile as well as traditional biomarkers and other biomarkers related with tissue inflammation and inflammatory response in diabetes patients including MMP 2&9, CRP, cystain C, creatinine, uric acid." (PMID 27917862, 2016). "Cases had significantly higher CRP, ESR and DAS28, and more impaired physical function (FFbH) and comorbidities (diabetes and chronic lung or renal disease)." (PMID 27495156, 2016). "Age, sex distribution, BMI, APACHEII score, history of hypertension and diabetes, radiotherapy parameters, Hb, WBC, and CRP were similar between euthyroid and LT3S patients." (PMID 26871787, 2016). "There is a clear association between the inflammatory biomarkers used to calculate the DII score (CRP, IL-1β, IL-6, TNF-α, IL-4, and IL-10) and cardio-metabolic diseases such as obesity, diabetes, or CVD." (PMID 27527152, 2016).